NRP1 (neuropilin 1)
Diseases named in the same sentence as NRP1 in open-access papers (continued):
Sharing a sentence is not in itself a finding about the gene and the disease.
tumor (continued). "The role of NRP1 as a coreceptor for FGFs in (tumor) vasculature is still unclear, as NRP1 may bind several FGFs but does not affect the FGF-2-induced proliferation of HUVECs." (PMID 30717262, 2019). "Unlike ECs, VM-lining tumor cells express NRP1, VEGF-C, TIE-1, endoglin, tissue factor pathway inhibitor (TFPI1), laminin subunit γ2 (LAMC2), and EphA2, whereas they do not express VEGF receptors -1 and -2, TIE-2, CD31, vascular adhesion protein-1 (VCAM-1) and P-selectin." (PMID 30717262, 2019). "Notably, NRP1 gene deletion in TAMs resulted in their entrapment in normoxic tumor regions and lack of infiltration in the tumor core, with a consequent reduction of their pro-angiogenic and immunosuppressive activities." (PMID 31052281, 2019). "Further, this study reports that PlGF promotes tumor cell survival through NRP1 and not VEGFR1." (PMID 31216652, 2019). "However, no significant change was observed in the NRP1 level in patients who had no tumor post NAC (n = 11, ypT0) or in patients who showed complete response to NAC (n = 8, pCR)." (PMID 31106153, 2019). "Moreover, neutralising anti-Nrp-1, anti-PD-1 and a combination of both mAb induced an increase in the percentage of CD8+ TIL expressing perforin after ex vivo stimulation with autologous tumour cells." (PMID 31350404, 2019). "Assessing patients who underwent NAC indicated that the levels of NRP-1 measured post-NAC were significantly higher in younger patients and patients with either a low or a medium body mass index (BMI), as well as in patients who remained with larger tumor size and partial response." (PMID 31106153, 2019). "Importantly, GAC biopsies showed the same vessel parameters and tumor proliferation irrespective of the presence of VEGFR2/NRP1 trans‐complexes, which occurred at low density." (PMID 30027561, 2018). "Therefore, NRP1 on vascular ECs was not accessible to blood-borne rhodocetin-αβ, ruling out that it targets ECs of tumor vessels primarily." (PMID 29854288, 2018). "Depletion of NRP1 in CD4+ T cells resulted in breakdown of tumor induced tolerance and activated antitumor immune response in tumor bearing mice, evident from increased CD8+ and reduced Treg cell infiltration into the TME, lesser tumor burden and improved tumor free survival." (PMID 29067024, 2017). "High NRP-1 expression is also involved in tumour resistance to VEGF-A blocking therapies, suggesting that inhibition of NRP-1 may be required to prevent compensatory escape mechanisms by tumour cells." (PMID 28977999, 2017). "Analysis of tumor cell proliferation in situ by double immunofluorescence using a human-specific vimentin antibody and anti-pSer10 Histone H3, a marker for mitotic cells, did not reveal Nrp1-dependent differences proliferation." (PMID 28938007, 2017). "In addition, adoptive transfer of NRP1 ablated T cells did not provide any survival benefit in tumor bearing mice, further indicating NRP1 was dispensable for tolerant phenotype in CD8+ T cells." (PMID 29067024, 2017). "Twenty-eight days after shNRP-1 minicircle delivery, rats demonstrated modest but significant NRP-1 knockdown along with basal increase in the endothelial markers, down-regulation of mesenchymal markers and TGFβ1-responsive Slug and CTGF expression and reduced tumor fibrosis." (PMID 27542226, 2016). "A dual role for NRP1 in VEGF- and ECM-driven angiogenesis during pathological angiogenesis may also explain why anti-VEGF and anti-NRP1 treatments have an additive effect in reducing tumour growth." (PMID 26923176, 2016). "Hypoxia suppressed miR-320 expression through HIF-1α and increased the expression of neuropilin 1 (NRP1) and promoted the motility and tube formation ability of endothelial cells via vascular endothelial growth factor (VEGF) signaling pathway, resulting in tumor angiogenesis." (PMID 26504785, 2015).
tumor (continued). "Interestingly, 24 h after tasquinimod exposure, mRNA expression of different angiogenic factors (Vegfc, Nrp-1, Fgf2, Il-6) was decreased in MCH-IIhigh macrophages compared to vehicle TAMs, suggesting that M1 macrophages contribute to tumor vasculature shrinkage." (PMID 26673090, 2015). "Additionally, the tumor-derived factors that lead to elevated Nrp1 in some but not all patients with similar cancers have not been defined and warrant further investigation." (PMID 25343644, 2014). "In other words, the gradient of NRP-1 and VEGFR-2 expression between the tumor and peritumoral tissue may attract VEGFA into the peritumoral tissue, where it combines with peritumoral NRP-1 and VEGFR-2 in hepatocytes, which may decrease tumor endothelial cell proliferation." (PMID 25333267, 2014). "NRP1 as multifunctional non-tyrosine-kinase receptors play critical roles in tumor progression." (PMID 24736504, 2014). "Scientists later found that NRP1 could boost tumorangiogenesis, accelerate tumor growth and curb tumor apoptosis without VEGFR." (PMID 24736504, 2014). "One is that the tumor tissue removed from mice for protein extraction not only included HCC cells, but also vascular endothelial cells (ECs), mononuclear cells and so on, which may have normal NRP-1 protein expression." (PMID 23251257, 2013). "This tumor cell derived NRP-1 is functionally active and may act as a positive modulator of tumor angiogenesis and a negative regulator of tumor cell apoptosis in the presence or absence of VEGF." (PMID 23563900, 2013). "NRP-1 functions as a coreceptor for the VEGFRs, enhancing their activity; however, NRP-1 may be able to signal independently of VEGFRs in response to VEGF, particularly in tumor cells." (PMID 23125933, 2012). "Therefore, we hypothesised that during the development of cancer, especially during the angiogenic process, the elevation of VEGF by tumour cells functions more than SEMA3A and NRP1 plays greater roles with VEGF than with SEMA3A." (PMID 22926477, 2012). "Thus, Sema 3A could act as a potent inhibitor of tumor angiogenesis by disrupting the interaction between VEGF and NRP1." (PMID 22448259, 2012). "However, the molecular effects and mechanism for NRP1-mediated signaling in tumor cells, especially in the absence of VEGF-Rs, remain elusive." (PMID 20085644, 2010). "These and other findings pose the problem of the mechanism through which VEGF acts in tumour cells, since the present study together with previous work shows that NRP1 is expressed in diverse tumour cells in the absence of significant expression of the major signalling VEGF receptor, VEGFR-2." (PMID 20087344, 2010). "Finally, the vast majority of free VEGF in the blood is VEGF165 (91%), regardless of the density of NRP1 in the tumor." (PMID 18713470, 2008). "This qualitative behavior is independent of the density of the NRP1 in the tumor." (PMID 18713470, 2008). "We tested the hypothesis that tumour-derived VEGF-C may play an autocrine role in metastasis by promoting cellular motility through one or more VEGF-C-binding receptors VEGFR-2, VEGFR-3, neuropilin (NRP)-1, NRP-2, and integrin α9β1." (PMID 17912247, 2007). "However, blockade of P38 MAPK inhibited EGF induction of both NRP-1 and VEGF and might be a therapeutic target in this tumour system." (PMID 12618892, 2003). "Similarly, CAFs express neuropilin-1 (NRP1) and integrins; TAMs may express DC-SIGN and ACE2; endothelial cells lining tumor vasculature express ACE2, NRP1, and integrins; and APCs like DCs express DC-SIGN (CD209) and L-SIGN, collectively enhancing OV tropism and entry." (PMID 40927720, 2025). "We have showed that PEI-elastase could lead to this protease uptake by NRP1 negative tumor cells." (PMID 39068444, 2024).
tumor (continued). "Importantly, SPC25 showed a significant positive correlation with COAD expressing many immune checkpoint genes, especially NRP1, CD276, TNFSF14, and other important immunotherapeutic targets, which may also be closely related to the immune escape mechanism of ACC tumor cells." (PMID 38605119, 2024). "However, ablation of Nrp-1 expression on CD8+ T cells did not affect acute tumor growth in mice." (PMID 38019895, 2023). "However, NRP1 still promotes tumor angiogenesis, in the absence of VEGFR." (PMID 35600336, 2022). "In conclusion, our findings show that the activity of endothelial NRPs together is required for sustained tumor angiogenesis, and support a hypothesis that maximum antiangiogenic efficacy can be achieved by cotargeting both NRP1 and NRP2 rather than targeting either receptor individually." (PMID 36970722, 2022). "Additionally, targeting the b1 domain of Nrp1 may compromise TGFβ and VEGF effects on myeloid cells, T cells and cancer stem cells, all of which are critical effectors in tumor progression, treatment resistance and tumor recurrence." (PMID 36203599, 2022). "In conclusion, the present study showed that upregulation of NRP-1 led to increased tumor motility in radiation-surviving tumor cells, which could be suppressed by the treatment of anti-NRP-1 antibody to a greater extent than the tumor cells before irradiation." (PMID 34698100, 2021). "Together, these findings provide insight into the roles of SHH, PlGF, and Nrp1 in SHH subgroup MB, and as PlGF is dispensable during development, they support the idea that this SHH tumor and PlGF interaction may be used as a therapeutic approach for this pediatric tumor." (PMID 34436033, 2021). "In addition, NRP1, PLXNB2, and PLXND1 also showed increased expression in immune subtype C3, which is correlated with better prognosis, indicating these genes may also play tumor suppressor roles in certain conditions." (PMID 32640719, 2020). "In addition, the results using the UALCAN database indicate that NRP1 mRNA expression was significantly increased in tumor tissues compared to in normal tissues, regardless of clinical characteristics, such as tumor stage, age, race, gender, and tumor grade of STAD using TCGA dataset." (PMID 32408477, 2020). "As NRP1 is a promiscuous coreceptor for different growth factor receptors, its depletion or inactivation may inhibit various signaling cascades starting from VEGFR2, EGFR, and MET, and thus, may aid to curb cell proliferation and tumor angiogenesis and oncogene addiction." (PMID 30717262, 2019). "Thus, we tested whether an anti-NRP-1 antibody could inhibit the tumor targeting and killing activity of TU17:MTD or not." (PMID 27083053, 2016). "However Nrp1 expression on human tumor-infiltrating CD8+ T cells has not been reported." (PMID 25343644, 2014). "However, several papers studying tumor cells lacking VEGFR-2 expression have suggested that NRP-1 may transduce VEGF-mediated signals either alone or in concert with other receptors." (PMID 23251257, 2013). "However, the functional significance of NRP-1 on tumour cells has not been elucidated." (PMID 15956974, 2005). "Unlike ECs, tumour cells may express NRP-1 as the only VEGF receptor." (PMID 12618892, 2003). "While the expression patterns and functional effects of NRP1 in non-neoplastic cells of the MB microenvironment remain poorly characterized, mapping the spatial and cellular distribution of NRP1 in tumor vasculature and glial cells may shed light on its role in tumor–microenvironment interactions." (PMID 40805120, 2025). "Nevertheless, both tumor and endothelial cells produce NRP-1 and other VEGF signaling molecules; therefore, the role of endothelial cells in tumor expression and activation cannot be ruled out." (PMID 40430075, 2025). "Nevertheless, no data indicate the importance of the oncogenic status of tumour cells, such as the oncogenic RAS protein in the cell signalling mediated by NRP-1." (PMID 40286084, 2025).
tumor (continued). "In both mouse models and humans, the absence of Nrp1 leads to fragile Tregs that secrete IFN-γ, inhibiting tumor growth." (PMID 39000453, 2024). "Glycoprotein NMB (GPNMB)-driven increases in NRP-1 expression in BC cells were reported to potentiate vascular endothelial growth factor (VEGF) signaling and tumor growth but not metastasis." (PMID 37175499, 2023). "Instead, ICB efficacy was robustly identified through the in situ hotspot detection of galectin-3-positive non-proliferating tumor zones enriched in cell death and infiltrated by anti-tumor cytotoxic neutrophils positive for ICAM-1 and neuropilin-1." (PMID 36672243, 2023). "Neuropilin-1 had a very similar pattern to that of ICAM-1, where it was expressed by non-proliferating rather than proliferating tumor cells and by (cytotoxic) neutrophils in both the proximal and border regions." (PMID 36672243, 2023). "We found that NRP1 was also detectable in HTPC-adeno and CRPC-Adeno specimens (data not shown) and primary luminal tumour samples, indicating that low NRP1 expression precedes transition to drug resistance." (PMID 36550208, 2023). "STAT6 can influence tumor angiogenesis through factors such as VCAM-1 and MMP, and NRP1 is not the only target molecule of STAT6." (PMID 35600336, 2022). "Although semaphorin-NRP1 signaling is not essential for vascular development in mouse embryos, semaphorin 3A (SEMA3A) participates in modulating tumor angiogenesis in mouse cancer models." (PMID 35600336, 2022). "Along these lines, short hairpin RNA-mediated depletion of NRP1, but not the use of NRP1-blocking antibodies, inhibited FGFR signaling and reduced tumor cell growth in vitro and in vivo." (PMID 33128042, 2021). "For example, disruption of the CARMA1–BCL10–MALT1 signalosome complex or targeting Nrp1 or Helios or ligation of GITR in Treg cells has been shown to destabilize TIL Treg cells and effectively control tumor without peripheral autoimmune effects reported." (PMID 34798898, 2021). "When MC38/Nb1 tumors were grown in CD8 T cell-depleted mice, tumor growth significantly increased and became indistinguishable from MC38/BCII10 control tumors, illustrating that anti-NRP-1 Nbs unleashed an efficient anti-tumor CTL response." (PMID 33266104, 2020). "The ATWLPPR peptide prevents VEGF165 interaction with NRP1 but not with VEGF-R2, and it has been shown to decrease tumor angiogenesis and tumor growth in vivo." (PMID 31027288, 2019). "As both neuropilin-1 and MET were only lumen-exposed in a subset of abnormal tumor vessels, but not in normal vessels, the prime target of rhodocetin-αβ were these abnormal tumor vessels." (PMID 29854288, 2018). "NRP1 and KDR expression was evaluated by manually scoring the frequency of dots in the tumor samples, with 0 for none detected, up to 3 for strong expression." (PMID 30027561, 2018). "As a non-tyrosine-kinase receptor, NRP1 can moderately increase the expression of the phosphorylation of Erk1/2, Akt, and P38MAPK to promote tumor cell proliferation and metastasis, as well as to curb the apoptosis and immune responses." (PMID 24736504, 2014). "Together, our data suggest that Nrp1 does not have an important role in the regulation of CD8+ T cell function or survival, and has no real influence on the dysfunctional phenotype of tumor/self-reactive CD8+ T cells." (PMID 25343644, 2014). "It has been shown that Nrp1 is able to bind VEGF-C; however, Nrp1 is not necessary for VEGF-C-induced tumor lymphangiogenesis." (PMID 23344023, 2012). "The current model includes NRP1 on muscle cells, and both NRP1 and NRP2 on tumor cells, which have not appeared in previous models." (PMID 22104283, 2011). "More interestingly, Bachelder's study found that NRP-1 supported VPF/VEGF autocrine function and further cell survival and chemotaxis in tumor cells lacking expression of VEGFR-1 and VEGFR-2." (PMID 18000534, 2007).
tumor (continued). "However, the potential functions and mechanisms of NRP1 and its homologous isoform, NRP2, in tumor progression and tumor immunology have not been fully elucidated." (PMID 37190154, 2023). "The group investigated a NRP1 mutant in which the cytoplasmic post synaptic density/drosophila disc large tumor suppressor/zonula occludens-1 proteins (PDZ) domain was deleted; under these conditions, Nrp1 failed to inhibit the phosphorylation of AKT at the immunological synapse and recruit PTEN." (PMID 36203599, 2022). "Compared with respective Cre-negative control tumors, only those depleted for both NRP1 and NRP2 saw a significant reduction in EDA-FN coverage around tumor vasculature, suggesting that both endothelial NRPs facilitate tumor angiogenesis by promoting vessel stability." (PMID 36970722, 2022). "Functionally, these soluble isoforms of NRP1 were reported to bind VEGF-A165, although not VEGF-A121, thus inhibiting VEGF-A165-induced phosphorylation of VEGFR-2 in endothelial cells resulting in reduced tumor growth (anti-tumor properties)." (PMID 30925751, 2019). "In two animal tumour models, this SV-CLRP does not primarily influence endothelial cells in normal vessels because of the inaccessibility of blood-borne rhodocetin-αβ to the basolaterally expressed neuropilin-1." (PMID 30823637, 2019). "In congruence with the findings on mouse T241 tumors expressing NRP1 or not on tumor cells, the presence of VEGFR2/NRP1 trans‐complexes in PDAC correlated with reduced vascular area, vessel count, vessel branching, and tumor proliferation, while the individual vessel area was not affected." (PMID 30027561, 2018). "In the absence of IL-10, impaired Treg-derived Nrp-1 suppressive functions and Foxp3 expression may be lost, allowing their transformation into effector CD4+ T cells to counteract tumor growth." (PMID 27075020, 2016). "In addition, placental growth factor acts through NRP1, rather than VEGF receptor 1, in order to promote tumor cell survival." (PMID 25954957, 2015). "Neuropilin 1 (NRP1), a non-tyrosine kinase transmembrane protein, functions as a co-receptor for VEGF, suggesting that NRP1 may have an important role in tumour angiogenesis." (PMID 26147006, 2015). "Neuropilin-1 (NRP-1), a VEGF co-receptor, was originally identified as a receptor for semaphorin 3, mediating neuronal guidance and axonal growth, that binds specifically VEGF165 but not VEGF121 on the cell surface of endothelial and tumor cells." (PMID 24066029, 2013).